REST (RE1 silencing transcription factor)
Diseases named in the same sentence as REST in open-access papers (continued):
Sharing a sentence is not in itself a finding about the gene and the disease.
cervical cancer (2 papers, 2022 to 2023). A primary or metastatic malignant neoplasm involving the cervix. "Technically, some of the genes analyzed in this study could be incorporated into a more extensive study to design a panel of biomarkers for the diagnosis and prognosis of cervical cancer and other REST-deficient cancers." (PMID 36984538, 2023). "In this work, we propose the potential role of REST downregulation on the expression of neural genes, which can serve as target molecules in the diagnosis of cervical cancer." (PMID 36984538, 2023). "Remarkably, an increase in the expression of the CHRNβ2 neuronal gene in HeLa cells was observed, which has been widely reported as a transcriptional target of REST and could be included in the panel of cervical cancer prognostic biomarkers." (PMID 36984538, 2023). "Background and Objectives: REST (RE1-silencing transcription factor) diminution is associated with transcriptional relaxation, neuropeptide overexpression, and phenotype redefinition in neuroendocrine cancers, but this effect has barely been studied in cervical cancer (CC)." (PMID 36984538, 2023). "To analyze this association, we first generated expression profiles of REST by immunostaining tissues corresponding to cervical intraepithelial neoplasia 1 (CIN 1, n = 9), cervical intraepithelial neoplasia 2/3 (CIN 2/3, n = 7), and cervical cancer (CC, n = 11), as well as HeLa and SiHa cell lines." (PMID 36984538, 2023). "Subsequently, the expression of REST, PROX1, and CHG-A in the non-neuroendocrine lung cancer cell lines H1299 and TKB5, the uterine cervical cancer cell line HeLa, and the neuroendocrine lung cancer cell line TKB16 was analysed by RT-PCR." (PMID 35094211, 2022).
channelopathy (2 papers, 2023 to 2024). Channelopathies are a group of diseases caused by the dysfunction of ion channel subunits or their interacting proteins. "However, it is noteworthy that the exposure to methylmercury exerts its neurotoxicity in ALS through the overexpression of Restrictive Element 1 Silencing Transcription factor (REST) and Piezo2 channelopathy is proposed to be a principal transcription activator." (PMID 38534336, 2024).
Coronary artery disease (2 papers, 2022). "Notably, the transcriptome data of the Framingham study showed that the levels of REST expression in coronary arteries were decreased in patients with coronary artery disease, than in healthy individuals." (PMID 35203469, 2022).
diffuse intrinsic pontine glioma (2 papers, 2020 to 2021). A neuroglial tumor that arises from the middle portion of the brain stem. "Recent studies indicated that REST modulates the vasculature in diffuse intrinsic pontine glioma (DIPG)." (PMID 32486064, 2020).
DiGeorge Syndrome (2 papers, 2012 to 2014). "ChIP-qPCR validation of TF binding to lncRNA gene promoters has elucidated numerous targets of key TFs, including non-conserved lncRNAs repressed by REST/NRSF in the human DiGeorge Syndrome critical region and in mouse." (PMID 25275320, 2014).
dilated cardiomyopathy (2 papers, 2013 to 2022). Cardiomyopathy which is characterized by dilation and contractile dysfunction of the left and right ventricles. "The resulting de-repression of REST target genes induces a cardiac phenotype with increased cellular energy consumption, resulting in postnatal dilated cardiomyopathy." (PMID 36230906, 2022).
gastric cancer (2 papers, 2017 to 2020). A primary or metastatic malignant neoplasm involving the stomach. "Interestingly, we found that ZFAS1 could directly bind with EZH2, LSD1 and CoREST (histone demethyltransferase of REST complex) in gastric cancer cells, which suggesting that ZFAS1 might also could regulate underlying targets at transcriptional levels." (PMID 27246976, 2017).
hippocampal atrophy (2 papers, 2017 to 2021). "This is not the first time that the NGS methodology pointed to a benign variants as protective (benign missense variant in REST gene is protective for hippocampal atrophy)." (PMID 34900593, 2021). "Two REST variants were genotyped in all patients: rs3796529, located in the VNTR and previously reported as protective for hippocampal atrophy in MCI and AD10, 11, and rs2227902, in linkage disequilibrium with the exon 4 VNTR in European populations." (PMID 28842657, 2017). "Overall, these findings, together with previous data, confirm a role of REST in hippocampal atrophy/preservation in neurogenerative disorders." (PMID 28842657, 2017).
Kleefstra syndrome (2 papers, 2022 to 2025). A genetic disorder characterized by intellectual disability, childhood hypotonia, severe expressive speech delay and a distinctive facial appearance with a spectrum of additional clinical features. "This pipeline rapidly identified Kleefstra syndrome in genetic variant cells compared to healthy cells, and revealed novel findings potentially implicating the key transcription factors REST and SP1 in disease pathogenesis." (PMID 35139903, 2022). "Here, we demonstrate that REST and SP1 interplay to co-ordinately regulate gene expression of a specific subset of genes associated with Kleefstra Syndrome." (PMID 35139903, 2022). "In addition, the study linked transcription factors REST and SP1 to disease specific changes relevant to Kleefstra Syndrome that portend pivotal cellular changes underpinning disease mechanism." (PMID 35139903, 2022). "Accordingly, during neural cell differentiation a consequence of the EHMT1 truncated protein may be disruption of the REST/EHMT1 complex, which leads to the perturbations in gene expression observed in Kleefstra Syndrome." (PMID 35139903, 2022). "In addition, transcription factors, REST and SP1, key to the etiology of Kleefstra syndrome were identified providing insight into disease mechanism which may facilitate the identification of drug targets for treatment." (PMID 35139903, 2022).
latent infection (2 papers, 2007 to 2021). "We propose that during the establishment and maintenance of latent infection, REST/NRSF binds to the HSV-1 RE-1/NRSE in a chromatin context and recruits CoREST/HDAC complexes." (PMID 17555596, 2007). "We predict this mechanism applies to HSV-1 latent infection since REST/NRSF is present in neurons." (PMID 17555596, 2007).
neuroendocrine carcinoma (2 papers, 2023 to 2024). A malignant neuroendocrine neoplasm composed of cells containing secretory granules that stain positive for NSE and chromogranin. "Our findings suggest that REST_SSO suppresses tumorigenesis in neuroendocrine cancers by restoring REST function." (PMID 39377066, 2024).
neuro‐ectodermal tumor (2 papers, 2021 to 2025). "However, we recognize that the inclusion of controls as neuronal or neuroectodermal tumor-derived cell lines, where REST expression is markedly higher, would further support the specificity of the scFv." (PMID 41465373, 2025).
prion disease (2 papers, 2016 to 2017). A transmissible disease that is caused by a protein that is able to induce abnormal folding of normal cellular proteins, leading to characteristic spongiform brain changes, which are associated with neuronal loss without an inflammatory response. "Despite these implications, the role and the associated molecular regulatory mechanisms of REST in prion diseases is poorly understood." (PMID 26919115, 2016). "We observed downregulation of REST, the inhibition of autophagy system-associated Akt-mTOR signaling pathway and the partially inactivation of the Wnt-β-catenin signaling pathway in the in vitro and in vivo prion disease models." (PMID 28515679, 2017). "Firstly, if REST acts as a neuroprotective regulator in prion diseases, what is the pattern of expression and distribution of REST in the brain of scrapie-infected experimental animals?" (PMID 28515679, 2017). "Our data illustrates that REST regulates neuron survival and is a critical neuroprotective factor in prion diseases and possibly other neurodegenerative disorders." (PMID 28515679, 2017). "Here we confirmed the findings of the in vitro model in 263K infected hamsters, an in vivo model of prion diseases and further showed the relationships between REST and related signaling pathways." (PMID 28515679, 2017). "In conclusion, REST plays a critical neuroprotective role partly via restoring the Akt-mTOR and Wnt-β-catenin signaling pathways in prion diseases." (PMID 28515679, 2017). "We further investigated the role of REST in the Akt-mTOR and Wnt-β-catenin pathways in our in vitro prion disease model." (PMID 28515679, 2017). "In summary, we propose a model to explain how REST-mediated neuroprotection is lost in prion diseases and further prove the important role of REST in mediating the upstream and downstream signaling pathways." (PMID 28515679, 2017). "Our findings and other published studies suggest that nuclear REST is a key factor of neuroprotection in prion diseases, AD and other neurodegenerative diseases." (PMID 26919115, 2016). "REST-mediated neuronal survival signaling could be explored as a viable therapeutic target for prion diseases and related neurodegenerative diseases." (PMID 28515679, 2017). "We postulated that the Akt-mTOR signaling pathway might be involved in REST suppression in prion diseases." (PMID 28515679, 2017). "Moreover, Wnt-β-catenin signaling, which partially induces the expression of REST under normal conditions, is suppressed in prion diseases." (PMID 28515679, 2017). "The relatively increased level of REST in the cortex of 263K-infected hamsters compared with the normal control in line with our previous in vitro experiments, suggesting the translocation of REST from nucleus to cytoplasm in prion diseases." (PMID 28515679, 2017). "In line with our previous study, the glycosylated form of LRP6 disappeared in the 263K infected group might be a potential reason to the downregulation of REST in prion disease." (PMID 28515679, 2017). "Collectively, we demonstrate for the first time novel neuroprotective function of REST in prion diseases and hypothesise that the LRP6-Wnt-β-catenin/REST signaling plays critical and collaborative roles in neuroprotection." (PMID 26919115, 2016). "Therefore, we further asked what the role of REST in the Akt-mTOR pathway is in prion diseases." (PMID 28515679, 2017). "Our recent study indicated that the transcription factor REST, a RE1-silencing transcription factor may function as a neuroprotector in prion diseases." (PMID 28515679, 2017).
retinoblastoma (2 papers, 2018 to 2024). A malignant tumor that originates in the nuclear layer of the retina. "The gene ontologies for list 6- linked CHTOP, FXR1, and REST to Retinoblastoma." (PMID 39480826, 2024). "We propose that CHTOP, FXR1, and REST are novel genes in Retinoblastoma." (PMID 39480826, 2024).
rheumatoid arthritis (2 papers, 2023 to 2025). A chronic, systemic autoimmune disorder characterized by inflammation in the synovial membranes and articular surfaces. "During rheumatoid arthritis (RA) pathogenesis, miR-137 is downregulated in association with the REST/mTOR axis, which is negatively correlated with inflammatory factors." (PMID 38138985, 2023).
acute pancreatitis (1 paper, 2020). An acute inflammatory process that leads to necrosis of the pancreatic parenchyma. "Furthermore, abrogation of REST activity in mice increased sensitivity to induced acute pancreatitis injury, suggesting that REST plays a protective function against exocrine pancreatic damage." (PMID 32080178, 2020).
adrenocortical cancer (1 paper, 2013). "Here, we have shown that SF-1 and NRSF/REST functionally interact in regulating gene expression in H295R adrenocortical cancer cells." (PMID 23907384, 2013). "An unexpected result of our study is represented by the discovery of a functional interaction of SF-1 with the transcription factor NRSF/REST in regulating gene expression in adrenocortical cancer cells." (PMID 23907384, 2013).
age-related hearing loss (1 paper, 2023).
age-related macular degeneration (1 paper, 2015). Age-related loss of vision in the central portion of the retina (macula), secondary to retinal degeneration. "We did not measure sight-impairment in our CC strains, however, a human GWAS of age-related macular degeneration identified a QTL at human chromosome 4q12 containing the following genes: REST, C4orf14, POLR2B and IGFBP733." (PMID 26548763, 2015).
astrocytoma (1 paper, 2023). "The analysis results revealed the higher REST mRNA expression in oligodendroglioma and astrocytoma compared with normal tissues (P < 0.001)." (PMID 36810892, 2023).
Beckwith-Wiedemann syndrome (1 paper, 2025). Beckwith-Wiedemann syndrome (BWS) is a genetic disorder characterized by overgrowth, tumor predisposition and congenital malformations. "Four patients had conditions with known WT associations (mosaic trisomy 18, isolated hemihyperplasia, REST gene mutation, and Beckwith-Wiedemann Syndrome)." (PMID 39779510, 2025).
Bladder Cancer (1 paper, 2026). "This study uncovers the novel mechanism by which HCN2 regulates ferroptosis via the REST-BGN axis, affecting bladder cancer cell behavior, and provides new perspectives and strategies for future clinical treatment." (PMID 42074076, 2026).
bone cancer (1 paper, 2016). A primary or metastatic malignant neoplasm affecting the bone or articular cartilage. "Here we demonstrate an important and previously unrecognized role for REST during the progress in bone cancer pain." (PMID 27732941, 2016). "In summary, our study provides the evidence that the negative regulation of REST on NR2B in spinal cord takes part in the exacerbation of bone cancer pain." (PMID 27732941, 2016). "During the progress of the bone cancer pain, the down-regulation in spinal REST (Neuron-restrictive silencer factor, NRSF/REST) with concomitant up-regulation in spinal NR2B (2B subunit of N-methyl-D-aspartate receptor, NR2B) protein expression are observed at days 5, 7, 10 and 14 post-inoculation." (PMID 27732941, 2016).
cardiac arrhythmia (1 paper, 2025). Any disturbances of the normal rhythmic beating of the heart or MYOCARDIAL CONTRACTION. "Therefore, the regulatory role of REST in the AVG neurons and cardiomyocytes could contribute to cardiac complications (such as cardiac arrhythmias and sudden cardiac death) in T2DM." (PMID 40427470, 2025).
cervical squamous cell carcinoma (1 paper, 2024). A squamous cell carcinoma arising from the cervical epithelium. "REST expression in human cervical squamous cell carcinoma (SCC) samples was lower than that of control samples by IHC; however, cervical SCC cell lines showed no statistical difference in REST expression compared to a benign cell line." (PMID 39273639, 2024).
clear cell renal cell carcinoma (1 paper, 2019). "Binding targets of SUZ12 and EZH2 were consistently enriched across all five cancer types, while targets of REST and SMAD4 were enriched in all cancers except for clear cell renal cell carcinoma." (PMID 31523055, 2019).
cocaine use disorder (1 paper, 2017). A substance-related disorder that involves the recurring use of cocaine despite negative consequences. "We strongly believe that REST protein through its targets and coordinated feedbacks with brain-related miRNAs can be an important element of molecular basis of cocaine use disorder; however, further analysis with using knockdown or overexpression approaches is requested to confirm it." (PMID 26944283, 2017).
colorectal tumors (1 paper, 2008). "REST was identified as a suppressor of human epithelial cell transformation and REST is frequently deleted in colorectal tumors." (PMID 18959480, 2008).
craniorachischisis (1 paper, 2023). Craniorachischisis is the most severe form of neural tube defect in which both the brain and spinal cord remain open to varying degrees. "For instance, variants in the CYP26B1 gene, occurring concurrently with other variants in neural tube-related genes such as CELSR3 and REST, were hypothesized to be associated with the craniorachischisis phenotype." (PMID 37424722, 2023).
febrile seizures (1 paper, 2024). "SE, induced by KA or experimental febrile seizures, increases nuclear accumulation of REST/NRSF and the binding of this transcription factor (TF) to the chromatin." (PMID 38641413, 2024).
Fever (1 paper, 2024). Body temperature elevated above the normal range. "REST/NRSF is also upregulated by SE provoked by experimental fever in developing rats." (PMID 38641413, 2024).
fractures (1 paper, 2022). "The signals in the other four genomic loci associated with hip fractures (REST, HOXC8, SALL1, and ETS2) were previously shown to associate with different BMD measures, supporting the notion that BMD is an important determinant also of hip fracture risk." (PMID 36260985, 2022).
hepatocellular carcinoma (1 paper, 2023). A malignant tumor that arises from hepatocytes. "In hepatocellular carcinoma (HCC), REST was found to be elevated in 27 of 49 human tissue samples, and it plays a key role in promoting diethylnitrosamine (DEN)-induced HCC initiation." (PMID 37892159, 2023).
hypoglycaemia (1 paper, 2025). "Our data show that prolonged treatment with 2DG is well tolerated by hippocampal neurons in vitro, increases REST/NRSF expression and its translocation to the nucleus and induces a reduction in the NADH/NAD+ ratio, as previously observed both in response to 2DG and hypoglycaemia." (PMID 41071623, 2025).
influenza (1 paper, 2025). An acute viral infection of the respiratory tract, occurring in isolated cases, in epidemics, or in pandemics; it is caused by serologically different strains of viruses (influenzaviruses) designated A, B, and C, has a 3-day incubation period, and usually lasts for 3 to 10 days. "REST downregulates viral genes during HSV-1 infection, while sialylated IgG leads to the upregulation of REST which suppresses and protects the host from NFkB mediated inflammation in influenza infection." (PMID 40006989, 2025). "Furthermore, REST induction was confirmed during therapeutic administration of recombinant sialylated Fc molecules in influenza virus-infected patients, offering protection against severe influenza disease." (PMID 40006989, 2025).
insulinoma (1 paper, 2021). "Next REST was overexpressed in the mouse insulinoma cell line MIN6 and gene expression was analysed by qPCR for Rest, Ins2, Pdx1, Snap25 and Scrt1 three days post infection." (PMID 33888791, 2021).
interstitial lung disease (1 paper, 2022). A diverse group of lung diseases that affect the lung parenchyma. "For example, the levels of miR-7 and miR-214-5p are significantly increased in the serum of patients with RA associated-interstitial lung disease, and miR-9-5p targets the REST/miR-132 pathway to protect Schwann cells from inflammatory damage in RA-induced peripheral neuropathy." (PMID 35401568, 2022).
lipid metabolic disorders (1 paper, 2021). "Second, we found that SARS-CoV-2 infection could modulate the expression of MPO, apelin, and myostatin by up-regulating transcription factor REST, which may lead to glucose and lipid metabolic disorders." (PMID 34916489, 2021).
liver cancer (1 paper, 2022). An epithelial or non-epithelial malignant neoplasm that arises from the liver. "Soon, when the new ChIP-seq and ATAC-seq become available, we hope to further examine REST’s role in liver cancer progression." (PMID 34996354, 2022). "HepG2 cell line is a liver cancer cell line where CEPB, REST and USF1 strongly contribute to chromatin accessibility." (PMID 34996354, 2022).
lung adenocarcinoma (1 paper, 2022). A carcinoma that arises from the lung and is characterized by the presence of malignant glandular epithelial cells. "Our findings indicate that the expression mechanisms of REST and/or PROX1 will help elucidate the transformation of lung adenocarcinomas into NECs." (PMID 35094211, 2022).